NPHP4 (nephrocystin 4)
Diseases named in the same sentence as NPHP4 in open-access papers:
NPHP4 is named in the same sentence as 58 diseases in open-access papers, as found by Europe PMC text mining. Sharing a sentence is not in itself a finding about the gene and the disease. The quoted sentences say what the papers report.
nephronophthisis (19 papers, 2005 to 2025). Progressive tubulointerstitial injury, inherited in an autosomal recessive pattern, caused by mutations in genes involved in ciliary function, which may result in an end stage renal failure. "In one family, homozygous pathogenic variants in two different genes (SPEN and NPHP4) were identified; to our knowledge, this is the first report of nephronophthisis and Radio-Tartaglia syndrome co- segregating in a family." (PMID 40730687, 2025). "Pathogenic NPHP4 variants are a known cause of Nephronophthisis, which is likely to account for the renal failure observed." (PMID 40730687, 2025). "NPHP4 is a cilia-associated protein that negatively regulates the mammalian Hippo signaling pathway and is linked to severe degenerative renal disease, nephronophthisis and blindness in humans." (PMID 38982489, 2024). "Both mutations classify our patient as SJ type 7 and his phenotype is justified by an impairment in the interaction with Nephrocystin-4, a protein associated with nephronophthisis." (PMID 38013309, 2023). "For example, PALS1-interacting proteins Nephrocystin-1 (NPHP1) and NPHP4 have been associated with nephronophthisis (NPHP), an autosomal recessive ciliopathic childhood cystic kidney disease." (PMID 35265622, 2022). "NPHP-4, a gene mutated in the cilium-related kidney disease nephronophthisis, is a crucial component of the ciliary gate that controls entry of both membrane-associated and soluble proteins." (PMID 31116988, 2019). "NPHP4 is a cilia-centrosomal protein mutated in nephronophthisis and SLSN." (PMID 20664800, 2010). "This is exemplified by the identification of a mutation in NPHP4 leading to cone-rod dystrophy a retinal degenerative disease in dogs, whereas in humans mutations in this gene are reported to cause both cone-rod dystrophy and nephronophthisis leading to end stage renal failure." (PMID 23933735, 2013). "These include Dent disease (CLCN5, OCRL), AD tubulointerstitial kidney disease (ADTKD due to UMOD variants), nephronophthisis (TTC21B, NPHP4), Imerslund-Grasbeck syndrome 1 (CUBN) and papillorenal syndrome (PAX2)." (PMID 37578539, 2024). "Seventeen patients carried heterozygous variants in at least one of 13 other genes (including NPHP4, RPGRIP1L, TMEM216, CC2D2A, and MKS1) implicated in nephronophthisis or associated syndromes, suggesting modified genetic activity." (PMID 37628633, 2023). "In the present study, we focused on the putative roles of nephrocystins NPHP1 and NPHP4, two proteins involved in nephronophthisis, in the processes of flow sensation." (PMID 37916190, 2023). "Like NPHP4, human mutations in NPHP1 are associated with multiple ciliopathies, including nephronophthisis and Joubert syndrome, characterized by cerebellar vermis hypoplasia." (PMID 26540106, 2015). "We found that RPGR associates with a ciliary protein nephrocystin-4 (nephroretinin; NPHP4) that is mutated in nephronophthisis (NPH) and RP (Senior-Løken syndrome)." (PMID 20664800, 2010). "NPHP4 is a candidate gene of nephronophthisis (NPH) and Senior–Løken Syndrome (SLS)." (PMID 33917198, 2021). "Mutations in human NPHP4 cause nephronophthisis, either with or without retinal degeneration." (PMID 26540106, 2015). "In this study, we applied an IF-based approach to a large cohort of 111 individuals with either nephronophthisis (n = 58) or other renal ciliopathies (n = 53) using antibodies directed against NPHP1 and NPHP4." (PMID 39098869, 2024). "Nephrocystins are responsible for a hereditary cystic kidney disease, nephronophthisis, and to date, nephrocystin 1 (NPHP1) through nephrocystin 4 (NPHP4) have been identified." (PMID 15693946, 2005). "Nephronophthisis (1 NPHP1, 1 NPHP4, and 1 TTC21B found in our study) may also be a differential diagnosis of ADTKD in young adults; however usually, autosomal recessive inheritance distinguishes it from ADTKD." (PMID 38707821, 2024).
nephronophthisis (continued). "The Renal proteinuria gene list corresponded to some genetic kidney diseases (CAKUT, tubulopathies, ciliopathies) that result in secondary FSGS such as Dent disease (CLCN5, OCRL), nephronophthisis (TTC21B, NPHP4), ADTKD-UMOD and Imerslund-Grasbeck syndrome 1 (CUBN)." (PMID 37578539, 2024). "In this case, sequencing and MLPA analysis of NPHP1 was also performed, together with the sequence analysis of other rarer genes related to nephronophthisis (INVS, NPHP3, NPHP4, IQCB1): no pathogenic variant was found in these genes." (PMID 37372410, 2023). "In the case of the transition zone complex components, Nphp4 and Nphp1 null mutant mice display male infertility without kidney phenotypes, in contrast to the human disease in which patients have severe nephronophthisis." (PMID 24415959, 2013).
ciliopathies (13 papers, 2014 to 2025). "To evaluate the meaning of the protein axis Nphp4‐Invs‐Nphp1 in the development of ciliopathies caused by mutations in Rpgrip1l, we investigated the phenotype of Nphp4−/− mouse embryos." (PMID 29650680, 2018). "SLS is a genetically heterogeneous renal–retinal ciliopathy associated with multiple ciliopathy-related genes, including NPHP1, NPHP4, IQCB1, and SDCCAG8." (PMID 40725491, 2025). "We also find that there is a mislocalization of a key transition zone gating and ciliopathy protein, NPHP-4." (PMID 31116988, 2019). "The identification of several new alleles of mks genes that cause a greatly exacerbated cilia phenotype in the presence of an nphp-4 mutation provides strong justification for this mutagenesis approach to identify modifiers of the NPHP and other ciliopathy phenotypes in C. elegans." (PMID 26863025, 2016). "Consequently, the very severe ciliopathy phenotype of Rpgrip1l−/− mouse embryos is not or not solely caused by the reduced Nphp4 amount in the absence of Rpgrip1l." (PMID 29650680, 2018). "Taken together, our analysis discovered a novel genetic interaction between two ciliopathy disease genes (RPI-1/DCDC2 and NPHP-4/NPHP4) in C. elegans." (PMID 37529113, 2023). "Genetic analysis is a powerful approach to revealing genetic interactions between two genes, and our genetic analysis helps us to uncover a novel genetic interaction between two ciliopathy disease genes (RPI-1/DCDC2 and NPHP-4/NPHP4) in C. elegans." (PMID 37529113, 2023).
cone-rod dystrophy (6 papers, 2009 to 2024). Inherited retinal dystrophies that belong to the group of pigmentary retinopathies. "Although no segregation could be established for this case with non-syndromic rod-cone dystrophy, an ultra-rare missense NPHP4 variant of uncertain significance (REVEL score = 0.328) was found exclusively in this individual." (PMID 38184646, 2024). "Similarly, a variant in NPHP4 is associated with recessive cone-rod dystrophy in Standard Wire-haired Dachshunds." (PMID 28322220, 2017). "Further, a mutation in NPHP4, another gene known to interact with RPGRIP1, was shown to be causative of cone/rod dystrophy of the wire-haired Dachshund." (PMID 22550515, 2012). "This fact is true for most forms of PRA; however, for the cone-rod dystrophies observed in the longhaired and shorthaired Dachshund breeds, with the RPGRIP1 and NPHP4 mutations, respectively, severe heterogeneity has been described for both." (PMID 22550515, 2012). "The mutation in NPHP4 causing an early-onset cone-rod dystrophy in the SWHD was not present in the MLHDs used in this study (data not shown)." (PMID 19936303, 2009).
Senior-Loken syndrome (5 papers, 2010 to 2025). Senior-Loken syndrome (SLSN) is a very rare autosomal recessive oculo-renal disease characterized by the association of nephronophthisis (NPHP), a chronic kidney disease, with retinal dystrophy. "In our cohort of 17 Korean patients with genetically confirmed Senior-Loken syndrome (SLS), four causative genes were identified: NPHP1 (35.3%), NPHP4 (29.4%), IQCB1 (29.4%), and SDCCAG8 (5.9%)." (PMID 40725491, 2025). "Mutations in NPHP4 and SDCCAG8 would cause Senior-Loken syndrome and Bardet-Biedl syndrome, these two disorders are characterized by LCA/RP and other systemic features including kidney conditions." (PMID 28456785, 2017). "The more C-terminal C2 domain of RPGRIP1L is responsible for binding to nephrocystin-4, and mutations in NPHP4 which cause Senior Loken Syndrome disrupt this interaction with RPGRIP1L." (PMID 21857984, 2011).
chronic kidney disease (4 papers, 2015 to 2025). Impairment of the renal function secondary to chronic kidney damage persisting for three or more months. "NPHP4 is involved in renal function and its mutations are known to cause juvenile end stage renal disease." (PMID 26578562, 2015). "One patient had chronic kidney disease from nephron phthisis and carried an NPHP4 variant." (PMID 34721897, 2021). "Among the five patients diagnosed with NPHP4-related SLS, two patients younger than 20 years old had moderate chronic kidney disease and ESRD, respectively, but showed normal visual fields and either normal or decreased cone response on the ff-ERG." (PMID 40725491, 2025).
retinal degeneration (4 papers, 2007 to 2025). Degeneration of the retina. "Humans with recessive mutations in NPHP1 and NPHP4 develop NPHP, and some patients develop retinal degeneration." (PMID 36533556, 2022). "NPHP4 interacts with retinitis GTPase regulator (RPGR) and RPGR-interacting protein 1 (RPGRIP1), potentially establishing a connection to the development of retinal degeneration in patients with an NPHP4 mutation." (PMID 40427560, 2025). "NPHP4 codes for an RPGRIP-interacting protein, and NPHP6 for an RPGR associated protein; both are good candidate modifier genes as, when mutated, they result in retinal degeneration." (PMID 17653054, 2007).
kidney failure (3 papers, 2022 to 2025). An acute or chronic condition that is characterized by the inability of the kidneys to adequately filter the blood. "Pathogenic NPHP4 variants cause nephronophthisis type 4, in which early-stage kidney dysfunction, or even kidney failure, is observed." (PMID 40730687, 2025). "This aligns with our NPHP4-related cases (Cases 9–11), where older patients exhibited severe diffuse RP with extinguished ERG responses and renal failure, while younger patients (Cases 7 and 8) showed preserved visual function and milder retinal involvement." (PMID 40725491, 2025).
male infertility (3 papers, 2013 to 2022). The inability of the male to effect fertilization of an ovum after a specified period of unprotected intercourse. "Truncation of NPHP4 caused male infertility by altering sperm quality." (PMID 36405559, 2022). "Other proteins that interact with filamin A, include the AR and nephrocystin 4 (NPHP4) and we found in HF conditions, a significant decrease in filamin interacting protein NPHP4, important for cytoskeleton signalling, cell adhesion and ciliary development and associated with human male infertility." (PMID 32678325, 2020).
renal failure (3 papers, 2021 to 2025). "A Renal Insufficiency Cohort (CRIC) identifies enhanced DNA methylation in genes of IQ motif and Sec7 domain 1 (IQSEC1), nephronophthisis 4 (NPHP4), and transcription factor 3 (TCF3) in participants with stable renal function while compared to those with rapid loss of eGFR." (PMID 33737884, 2021).
retinal ciliopathy (3 papers, 2024 to 2025). "In canine models of naturally occurring retinal ciliopathy, homozygous variants in genes such as NPHP4, NPHP5, and RPGRIP1 have been identified as causes of CRD,51–53 despite these genes being similarly expressed in both rods and cones." (PMID 39898911, 2025). "In canine models of naturally-occurring retinal ciliopathy, homozygous variants in genes such as NPHP4, NPHP5, and RPGRIP1 have been identified as causes of CRD, despite these genes being similarly expressed in both rods and cones." (PMID 38979372, 2024).
cyst (2 papers, 2015 to 2025). A sac-like closed membranous structure that may be empty or contain fluid or amorphous material. "Association of ANKS3with ciliary abnormalities, its interaction with nephronophthisis proteins (NPHP1, NPHP4, NPHP8) and its role in cyst formation have been demonstrated following ANKS3 knockdown in zebrafish." (PMID 26327442, 2015).
Dent disease (2 papers, 2024). Dent disease is a rare genetic renal tubular disease characterized by manifestations of proximal tubule dysfunction. "UMOD, CLCN5, OCRL, NPHP4, and TTC21B may cause tubulointerstitial diseases such as ADTKD, NPHP, or Dent disease, but they are now included in the genetic panels for genetic screening of patients affected by FSGS, as they can phenocopy it." (PMID 37728640, 2024).
Hepatic fibrosis (2 papers, 2023 to 2025). The presence of excessive fibrous connective tissue in the liver. "Homozygous NPHP1 possibly modified by heterozygous NPHP4 with early-onset ESKD;Compound heterozygous NPHP3 modified by heterozygous NPHP4 variant with early-onset ESKD and hepatic fibrosis;TTC21B contributes possible modifier alleles to NPHP4." (PMID 37628633, 2023).
polycystic kidneys (2 papers, 2009 to 2022). "Interestingly, nephrocystin-4 is conserved in the nematode Caenorhabditis elegans, which exhibits male mating phenotype defect upon Nphp4 knockdown, a phenotype also observed with orthologs of polycystic kidney disease genes." (PMID 18607645, 2009).
renal fibrosis (2 papers, 2022 to 2026). A final common manifestation of a wide variety of chronic kidney diseases characterized by glomerulosclerosis and tubulointerstitial fibrosis. "Impairment of NPHP4 was found to be associated with renal fibrosis and cystogenesis in nephronophthisis." (PMID 35806113, 2022). "In the context of renal fibrosis phenotype ontology (RENAL_FIBROSIS), upregulation was observed in ANTXR1, MUC1, SLC37A4, and NPHP4, while ARL3 and NPHP3 were significantly downregulated." (PMID 41573374, 2026). "Nephronophthisis 4 (NPHP4), transcription factor 3 (TCF3), and IQ motif and Sec7 domain 1 (IQSEC1) were found to be involved in pathways that promote the epithelial to mesenchymal transition and renal fibrosis." (PMID 35806113, 2022).
albinism (1 paper, 2023). A congenital disorder characterized by partial or complete absence of melanin pigment in the eyes, hair, or skin. "Other diagnoses detected among Africans include albinism (GPR143 and TYR genes), Senior–Loken Syndrome (NPHP4 gene), and X-linked retinoschisis (RS1 gene)." (PMID 36836473, 2023).
autosomal recessive spastic paraplegia (1 paper, 2022). "Examples include SPG11 (MIM# 610844) associated with autosomal recessive spastic paraplegia, RAB3GAP2 (MIM# 609275) linked to autosomal recessive Marsolf syndrome, and NPHP4 (MIM# 607215) linked to autosomal recessive nephronophthisis." (PMID 35330423, 2022).
collagenopathies (1 paper, 2024). "Genetic findings that modified the diagnosis in 19 patients included mutations in patients with NPHP (NPHP1 [n = 4], TTC21B [n = 3], ANKS6 [n = 1], NPHP3 [n = 1], NPHP4 [n = 1]), collagenopathies (COL4A5 [n = 7], COL4A3 [n = 1]), and Fabry disease (GLA [n = 1])." (PMID 39363361, 2024).
colorectal cancer (1 paper, 2024). A primary or metastatic malignant neoplasm that affects the colon or rectum. "cg09317508 is positioned near the Nephrocytin 4 gene (NPHP4), a WNT pathway gene and is upstream of microRNA MIR4689, which has been reported to interact with KRAS and AKT in colorectal cancer." (PMID 38554236, 2024).
developmental delay (1 paper, 2021). "RPGRIP1L and RPGRIP1 are known to interact with the NPHP4 C2 domain, and mutations in both can cause developmental delay by interfering with neuronal development." (PMID 34722527, 2021).
herpesvirus infections (1 paper, 2025). "None of the differentially regulated genes were linked to antiviral immunity associated with herpesvirus infections (for example, MX2, IFI16, CGAS, IFITs and OASs32,82–84), indicating that the anti-VZV function of NPHP4 is probably independent of the innate immune defence." (PMID 40739040, 2025).
nephronophthisis type 1 (1 paper, 2010). "It has been shown that NPHP4 interacts with NPHP1 (nephrocystin), which is a ciliary protein mutated in nephronophthisis type 1 and which localizes to photoreceptor CC." (PMID 20664800, 2010).
Oculomotor apraxia (1 paper, 2009). Ocular motor apraxia is a deficiency in voluntary, horizontal, lateral, fast eye movements (saccades) with retention of slow pursuit movements. "Twenty-three different NPHP4 mutations were found in 26 (10%) unrelated patients (13 with isolated NPH, eight with RP, and two with oculomotor apraxia)." (PMID 18607645, 2009). "Direct sequencing of the NPHP4 gene has been performed in 250 individuals, 190 with isolated NPH, 50 with RP and ten with oculomotor apraxia." (PMID 18607645, 2009).
retinal disease (1 paper, 2014). "Because the affected dogs did not share common alleles, we excluded single, fully penetrant mutations in six known canine retinal disease genes: BEST1, PDE6B and PDE6A, RPE65, NPHP4, and CNGB3." (PMID 25198798, 2014).
Type II Diabetes (1 paper, 2020). "We found that our false positive associations with genes WFS1, HNF4A, NPHP4, and TXNL4B were reported to be associated with Type II Diabetes in GWAS Catalog while the others were not." (PMID 33206638, 2020).
kidney disease (4 papers, 2018 to 2025). "NPHP4-mutated cases typically had progressed renal disease at diagnosis, with variable ocular involvement depending on age." (PMID 40725491, 2025).
infection (1 paper, 2025). The state of being infected such as from the introduction of a foreign agent such as serum, vaccine, antigenic substance or organism. "To further decipher the function of NPHP4, we used transcriptome analysis of NTC and NPHP4-deficient SK-N-BE2 cells that were mock infected or VZV infected using a transwell co-culture infection system." (PMID 40739040, 2025).
kidney (1 paper, 2024). "In addition, two compound heterozygous variants NM_015102.5:c.[1196A>G(p.E399G)];[1972C>T(p.R658*)] in NPHP4 gene were also identified in the fetus, which may be partially responsible for fetal kidney hyperechogenicity and oligohydramnios." (PMID 39877340, 2024).
NPHP4 also shares sentences with these, for which no sentence is quoted: cystic kidney disease (4 papers); Bardet-Biedl syndrome (2); end stage renal disease (2); Alport syndrome (1); and retinal (1); benign recurrent intrahepatic cholestasis type 2 (1); Blindness (1); cholestasis (1); Fabry disease (1); homocysteinemia (1); Intellectual disability (1); Joubert syndrome (1); Kidney Cyst (1); Lowe syndrome (1); lung carcinoma (1); lymphoblastic leukemia (1); meningoencephalitis (1); Methylmalonic aciduria (1); nephronophthisis type 4 (1); nephrotic syndrome (1); premature ovarian failure (1); Radio-Tartaglia syndrome (1); renal dysplasia (1); retinal dystrophies (1); retinitis pigmentosa (1); scoliosis (1); Senior-Løken syndrome (1); transposition of the great arteries (1); Usher syndrome (1); X-linked retinoschisis (1).